CXCL14 (C-X-C motif chemokine ligand 14)
Diseases named in the same sentence as CXCL14 in open-access papers (continued):
Sharing a sentence is not in itself a finding about the gene and the disease.
tumor (continued). "The specific molecular mechanisms through which CXCL14 suppresses tumor growth are unclear." (PMID 31014014, 2019). "Transplanting MC57-CXCL14 cells into the back skin of C57BL/6 mice resulted in the formation of smaller tumors compared with those transplanted with control MC57-MOCK cells, suggesting that CXCL14 expression in mesenchyme-derived cells also suppresses tumor growth." (PMID 31014014, 2019). "Thus, we investigated the effects of fasudil, a specific inhibitor of ROCK, on CXCL14 secretion and tumor progression in these cells." (PMID 31014014, 2019). "In patient tissues, we confirmed CXCL14 protein expression by IHC, and provided an indication that it is expressed in the cytosol and extracellular region of reactive astrocytes, strongly infiltrating tumor samples." (PMID 31117166, 2019). "Finally, we observed in vivo tumor growth suppression when YCU-H891 cells were engineered to express CXCL14 ectopically in the presence of doxycycline." (PMID 31014014, 2019). "Additionally, injection of DAC together with cetuximab in YCU-H891 tumor-bearing mice stimulated CXCL14 expression in the tumor and suppressed tumor growth, indicating that CXCL14 was a marker for tumor suppression by cetuximab." (PMID 31014014, 2019). "CXCL14 is elevated in tumor stromal cells and promotes tumor cell proliferation and metastasis." (PMID 30603053, 2018). "Additionally, mCAFs abundantly expressed the immune cell-attracting factor CXCL14, suggestive of a role in the regulation of the tumor immune response." (PMID 30514914, 2018). "Interestingly, we have previously found that high-risk HPV E7 significantly reduces NK and CD8+ T cell infiltration into the HPV-positive tumor microenvironment through CXCL14 downregulation by its promoter hypermethylation." (PMID 28623356, 2017). "Finally, we observed in vivo tumour growth suppression when YCU-H891 cells were engineered to express CXCL14 ectopically in the presence of doxycycline." (PMID 27399917, 2016). "To determine whether adaptive immune responses are involved in Cxcl14-mediated tumor suppression, we examined the tumor growth from these clones in Rag1-deficient C57BL/6 mice (Rag1−/−)." (PMID 27143385, 2016). "Importantly, Cxcl14 expression in HNC cells suppresses tumor growth from xenografts in athymic nude and SCID mice." (PMID 27143385, 2016). "In this study, using methylation levels of the CXCL14 promoter as a marker, we investigated whether DNA hypermethylation contributes to the tumour-suppressive effect of cetuximab." (PMID 27399917, 2016). "Interestingly, tumor growth was moderately slowed by Cxcl14 reexpression in Rag1−/− mice up to 14 days postinjection." (PMID 27143385, 2016). "Interestingly, restoration of Cxcl14 expression recruits DCs into tumors in vivo and in vitro and induces tumor necrosis." (PMID 27143385, 2016). "The rate of survival was always significantly higher, P < 0.005 (3 × 103 cells), P < 0.005 (1 × 104 cells), P < 0.0001 (1 × 105 cells), in the Tg mice than in the Wt mice, indicating that high expression of CXCL14 increased the survival rate as well as decreased tumour cell metastasis." (PMID 25765541, 2015). "In conclusion, we demonstrated that CXCL14 Tg mice showed a suppressed rate of carcinogenesis, decreased tumour volume, and reduced pulmonary metastasis, as well as an increased survival rate of mice following tumour cell injection." (PMID 25765541, 2015). "Although the role of CXCL14 as a tumor suppressor seemed well established, recent studies suggested that CXCL14 might actually promote tumor progression." (PMID 23294544, 2013). "The functional role(s) of CXCL14 in tumor biology has been addressed in a few previous reports." (PMID 23294544, 2013). "Additionally, the levels of CXCL14 expression were significantly associated with some clinicopathologic factors including TNM stage, histodifferentiation, and tumor size." (PMID 23294544, 2013).
tumor (continued). "In order to investigate whether CXCL14/BRAK has a tumor-suppressing effect in vivo, we prepared CXCL14/BRAK-expression vector-transfected and mock vector-transfected tongue tumor cells." (PMID 23762619, 2012). "The effects of CXCL14/BRAK expression were examined by measuring the tumor size." (PMID 23762619, 2012). "For example, two chemokines (chemokine (C-X-C motif) ligand (CXCL) 12 and CXCL14) that bind to tumor epithelial cells to promote proliferation, migration and invasion have recently been shown to be overexpressed by the activated tumor fibroblasts and myoepithelial cells." (PMID 19187537, 2009). "Additionally, in vivo studies using a subcutaneous tumor model showed that CXCL14 not only suppressed tumor growth but also enhanced the infiltration of immune cells, including NK cells, dendritic cells (DCs), and T cells, converting the tumor microenvironment from a "cold" to a "hot" phenotype." (PMID 42193871, 2026). "Notably, plasma levels of CXCL14 in LUAD patients correlate significantly with tumor stage." (PMID 40162549, 2025). "Our data suggest that, in the PAC context we studied, CXCL14-expressing malignant ductal cells may help establish immunosuppressive interactions with M0 macrophages, potentially contributing to immune evasion or tumor progression." (PMID 40666516, 2025). "Interestingly, tumors from mice that did not respond had a lower expression of CXCL14, and a loss of ability to express CXCL14 by CD11b+, a marker for monocytes, granulocytes, and NK cells, coincides with a loss of response to VEGF therapy and the return of tumor angiogenesis." (PMID 38339310, 2024). "Additionally, CXCL14 may also be involved in a tumor-progressing metabolic mechanism, such as the uptake of glucose, which was observed to be inhibited by CXCL14." (PMID 38400076, 2024). "Furthermore, QZACP induced irreversible cell cycle arrest in stressed tumor cells by up-regulating the expression of p21 and promoting the secretion of PASP factors (decorin, CXCL14, and Wnt family member 2) within tumor cells after recruiting NK and CD8+ T cells." (PMID 39206194, 2024). "CXCL14, also known as Breast- and Kidney-Expressed Chemokine (BRAK), is mainly expressed in healthy epithelial tissues such as epithelial cells, adipose tissues, intestines, mast cells, and kidneys, and is also detected in tumor cells, fibroblasts, and macrophages." (PMID 39334887, 2024). "Interestingly, through cell communication analysis, it was found that the highly expressed CD47 in the CXCL14+ tumor cell subgroup can bind to SIRPA on the macrophage membrane, delivering a "self-signal" that prevents the subgroup from being phagocytosed by macrophages." (PMID 37858183, 2023). "Thus, CXCL14 modulates the tumor microenvironment and enhances anti-tumor immunity." (PMID 36012586, 2022). "Also, CAFs expressed CXCL14 for their tumor-supporting properties." (PMID 36119108, 2022). "In addition, CAFs secrete cytokines like CCL7, CXCL12, and CXCL14 that favour tumour progression." (PMID 36555218, 2022). "However, current knowledge regarding the potential function of CXCL14 in immunotherapy is limited only to the recruitment of NK and/or T cells to the tumour microenvironment, whereas the mechanism by which CXCL14 suppresses tumour development remains unclear." (PMID 33733587, 2021). "CXCL14 may play distinct roles even in the same type of tumor." (PMID 34744744, 2021). "The clinical correlation of this biomarker with disease prognosis remains unclear at this time, as several have reported that elevated levels of CXCL14/BRAK expression in tumor sections correlates with worse overall survival, yet others have reported the opposite." (PMID 34611474, 2021). "In addition, CXCL14 expression is inversely correlated with EGFR expression in tumor cells." (PMID 34696665, 2021). "Furthermore, CXCL14 has been demonstrated to have both tumor-suppressive and pro-oncogenic roles." (PMID 34789307, 2021).
tumor (continued). "Thus, GPR85 may be a good target molecule for further clarification of context-dependent CXCL14 functions on tumor progression." (PMID 31014014, 2019). "To further investigate whether carcinoma-associated cells suppressed the growth of tumor cells other than HNSCC cells in a paracrine or endocrine manner, we produced CXCL14-overexpressing transgenic mice and examined the growth of tumor cell transplants in these mice." (PMID 31014014, 2019). "Alternatively, the presence of other molecules in addition to CXCL14 may also affect tumor growth." (PMID 31014014, 2019). "Thus, it appears that CXCL14 action in cancer is dependent on the tumor type." (PMID 31117166, 2019). "Indeed, it has been recently reported that CXCL14/BRAK transgenic mice display a significant lower rate of induced colorectal carcinogenesis, decreased tumor size when injected with tumor cells, and reduced number of lung metastatic nodules in comparison with wild-type mice." (PMID 30591657, 2018). "Additionally, the recently identified CXCL14 can modulate tumor immune cell infiltration." (PMID 30591657, 2018). "Thus, CXCL14 has been suggested as a potential tumor suppressor having anti-inflammatory functions." (PMID 27143385, 2016). "A case-control study involved with 361 HBV-related HCC cases and 407 healthy controls also supports our finding, it has been revealed that the polymorphism in CXCL14 was associated with the HCC progression, suggesting that CXCL14 might alter the disease development by inhibiting tumor growth." (PMID 27769059, 2016). "Hence it could conceivably be hypothesized that CXCL14 could be an important tumor suppressor in HBV-related HCC, and investigation on the underlying mechanism should be conducted." (PMID 27769059, 2016). "Thus, our findings suggest that CXCL14, secreted by epithelial cells, might be one of the key regulators for NK, CD4+ T, and CD8+ T cells to drive tumor clearance during HPV-associated cancer progression." (PMID 27143385, 2016). "Thus, TME at primary site increases tumor dispersion via paracrine signals by generating a chemotactic relay system, a case that can be further exemplified by CXCL14 secreted by CAFs, or EGF and CXCL5 released by tumor-associated dendritic cells in prostate and lung tumors, respectively." (PMID 25857315, 2015). "Numerous reports have implicated CXCL14 in cancer but findings disagree whether this chemokines displays anti-tumor as opposed to tumor-promoting activity." (PMID 22837760, 2012). "Combined bioinformatics and experimental analyses reveal that PSMD2 downregulates chemokine (C-X-C motif) ligand 14 (CXCL14) expression and secretion via the MAPK pathway, thereby remodeling the immune microenvironment and driving tumor progression." (PMID 41930182, 2026). "Further analysis of oncogenes and tumor suppressor genes revealed that tumors exhibited elevated expression of oncogenes such as ZWINT and ZIC4, and decreased expression of tumor suppressors like HAMP and CXCL14." (PMID 41388520, 2025). "CXCL12 facilitates tumor invasion and metastasis, while CCL11, CXCL14, CCL6, and CCL12 further contribute to chemoresistance and metastasis by enhancing glycolysis." (PMID 40230452, 2025). "The expression levels of the genes CD36, CXCL14, DAB2, MARCKS, ENPEP, and TIMP1 in normal, tumor, and metastatic tissues were analyzed using various statistical methods." (PMID 40565366, 2025). "Some of the genes, such as THBS1, CXCL14, and DMBT1, were notably enriched in AS_EP_STAS, suggesting their crucial role in the process of tumor cell spread into air spaces." (PMID 40786043, 2025). "The direct contact and close interaction between transitional CXCL14+ myCAFs and promoting metastasis factors, such as EMT tumour cells and angiogenesis, were revealed by the spatial data." (PMID 40162549, 2025).
tumor (continued). "To assess the duration of CXCL14 action in the tumor microenvironment and its potential for reversing drug resistance, we blocked CXCL14 in CAF/CM by adding either IgG or a CXCL14 neutralizing antibody." (PMID 40898244, 2025). "Of note, we noticed that CXCL14+ myCAFs (CAF‐C11), another subset of myCAFs, mainly existed in the advanced‐stage LUAD tumours." (PMID 40162549, 2025). "Regulation of differentiation of CXCL14+ fibroblasts and dysregulation of ECM organization to restrict immune cell tumor infiltration in pMMR." (PMID 41450739, 2025). "Next, we performed the co‐injection of 3T3 Cxcl14‐OE cells with mouse LLC cells, either subcutaneously or orthotopically, into immune‐competent C57BL/6 mice led to a substantial enhancement in tumour growth compared to the control group." (PMID 40162549, 2025). "Interestingly, single cell-RNA sequencing has revealed that CXCL14 downregulation is most prominent in malignant cells within tumor-draining lymph nodes as well as the primary tumor cells, suggesting that CXCL14 may play an important role in limiting nodal metastasis." (PMID 38400076, 2024). "In a more detailed analysis, we found that among 28 subsets of tumor-infiltrating lymphocytes, 22 were correlated with CXCL2, 21 with CXCL12, 15 with CXCL14, and 19 with CXCL17." (PMID 38232115, 2024). "Several genes particularly CXCL14, COX6C, CRISP3, and MPG with high expression levels in these tumor regions were identified, while healthy cells exhibited few significant genes, with only MALAT1 observed." (PMID 39764614, 2024). "Further investigations are required to elucidate the regulatory mechanisms behind CXCL14 expression that enhance CD8+ T‐cell recruitment, along with the resulting anti‐tumour actions of these cells." (PMID 39095323, 2024). "Bidirectional crosstalk between tumor cells and CAFs enhances the ability of fibroblasts to secrete various pro-tumor chemokines, including CXCL12/CXCR4 axis, CCL2, CCL5, CCL7, CXCL8, and CXCL14." (PMID 39092186, 2024). "The patients with low TFRC expression showed high expression of CXCL14 and harboured significantly more CD8+ T cells in tumour tissues compared with the patients with high TFRC expression (all p‐values < 0.05)." (PMID 39095323, 2024). "Previous evidence suggests that tumor cell HK3 can reduce its secretion of lactate and cell communication factors, including CXCL14, thereby indirectly affecting the polarization of macrophages toward an M2-like phenotype and influencing tumor progression." (PMID 38714539, 2024). "By rescuing the expression of CXCL14 in HPV+ HNSCC cells, we observed increased MHC-I expression and CD8+ T cell infiltration into the TME, resulting in tumor suppression in vivo." (PMID 38400076, 2024). "CXCL14 (log2FC = − 2.73, adjusted p-value < 0.001) and NTN4 (log2FC = − 1.89, adjusted p-value < 0.001) were differentially expressed in stromal and tumor regions, respectively." (PMID 39135097, 2024). "Lastly, CXCL14 has dual functions in enhancing antitumor responses by recruiting natural killer (NK) and T cells into the TME and upregulating MHC-I expression on tumor cells to enhance antigen presentation." (PMID 38400076, 2024). "On the other hand, the CCL28, CXCL14 and CX3CL1 expression levels were higher than those in other tumours." (PMID 37484803, 2023). "The basal tumor cells of cSCC samples in our study highly expressed CCL2, CXCL14, FTH1, MT2A, which is consistent with the findings in Tumor_KC_Basal." (PMID 38099574, 2023). "A recent study has indicated that CXCL14 can recruit and activate CD8+ T cells in vitro and in vivo, and favor the anti-tumor CD8+ T-cell response in LGG." (PMID 37848933, 2023). "Conversely, FAT-WT patients had suppressive TME with high expression of CCL2, CXCL12, CXCL14, CD40, ENTPD1, TGFB1, and VEGF; these factors have been confirmed to promote angiogenesis, invasion, and metastasis of tumor cells." (PMID 35836939, 2022).
tumor (continued). "CXCL14-induced decrease in Treg cells and increase in CD8+ T cells in primary tumors and metastatic lungs likely contributed to the tumor-inhibitory effects of CXCL14." (PMID 36012586, 2022). "The tumor-infiltrating lymphocytes most closely related with CEMIP expression in BC were CCL7, CCL14, CCL20, and CXCL14." (PMID 35370456, 2022). "In our integrated analysis of human colon mucosa and tumor fibroblasts, PDPN was prominently expressing in CXCL14+INHBA+ fibroblasts." (PMID 36463319, 2022). "Here, we investigated if CXCL14 plays a critical role in TNBC progression, focusing on survival rates, tumor growth and metastasis, and immune profiles in the tumor microenvironment." (PMID 36012586, 2022). "Mechanistically, tumor cell–derived FGF-2 strongly promoted pericyte proliferation and pericyte-specific expression of an orphan chemokine (C-X-C motif) ligand 14 (CXCL14) via FGFR1/AHR signaling." (PMID 35439170, 2022). "By contrast, HPV infection downregulates CXCL14, leading to a possible suppression of the chemotaxis of NK, CD4+ T, and CD8+ T cells, which in turn suppresses the anti-tumor immune response in the TME." (PMID 35740551, 2022). "CAFs-3 from the primary tumor showed distinct expression of other chemokines and growth factors, such as C3, CCL5, IGF1, CXCL10, CXCL9, and CXCL14, in addition to CCL19 and IGF2." (PMID 34790166, 2021). "The result shows that in tumor cells, PMEPA1 were negatively correlated with some chemokines (including CXCL1, CXCL11, CXCL2, CXCL8, CX3CL1) and positively correlated with CXCL14 and LAG3." (PMID 34777336, 2021). "As expected, the tumour volume and weight were significantly increased when CDX2 was knocked down, both of which effects were remarkably decreased after restoration of CXCL14." (PMID 33733587, 2021). "We found that CXCL14, TGFβ1, and TNFSF10 were highly expressed in tumor tissues compared with adjacent normal samples." (PMID 34167551, 2021). "In the current study, we also found that especially four chemokines were upregulated in the recurrent tumor compared to the primary tumor; CCL13, CCL18, CCL19, and CXCL14." (PMID 33352957, 2020). "In murine models of head/neck and cervical cancers, restoring Cxcl14 expression in HPV-positive cancer cells dramatically increased NK and T cells in the tumor-draining lymph nodes, leading to potent anti-tumor responses in vivo." (PMID 31337018, 2019). "The chemokines CXCL14 and CXCL12 are overexpressed in tumor myoepithelial cells and myofibroblasts, respectively, as demonstrated in a study using serial analysis of gene expression." (PMID 31014014, 2019). "In an attempt to identify the mechanisms responsible for tumor suppression, we screened for molecules downregulated in a cancer progression model and found that the chemokine CXCL14, also called BRAK, was the most significantly downregulated." (PMID 31014014, 2019). "The correlations between the mRNA expression levels of CXCL14, CXCL16, and CXCL17 in the primary tumor tissues were assessed by a two-tailed Spearman’s rank order correlation test." (PMID 31752131, 2019). "Others like HOXD8rc, CXCL14, SLC16A5rc, and GRASP were recovered more frequently from patients with higher Gleason grade and higher tumor volume making them potential candidates for predictive or prognostic panels and for disease monitoring." (PMID 31297302, 2019). "Thus, our data suggested that CXCL14 could act as a tumor suppressor." (PMID 31014014, 2019). "Restoration of CXCL14 expression in HPV-positive cancer cells significantly increases NK and T cell recruitment and dramatically suppresses tumor cell growth in vivo." (PMID 29438328, 2018). "Consistently, ectopic expression of CXCL14 in HCC cells decreases colony formation, cell viability, cell invasion, and tumor growth in vitro and in vivo." (PMID 29438328, 2018). "In contrast, 5 and 7 out of 10 mice transplanted with Cxcl14-reexpressing MOE/E6E7 clones 8 and 16, respectively, were tumor-free up to 11 weeks postinjection." (PMID 27143385, 2016).